ALK (ALK receptor tyrosine kinase)
Diseases named in the same sentence as ALK in open-access papers (continued):
Sharing a sentence is not in itself a finding about the gene and the disease.
anaplastic large cell lymphoma (continued). "In the case of crizotinib, only NSCLC patients were included in the clinical trials, even though ALK gene fusion was originally found in anaplastic large cell lymphoma (ALCL) as well." (PMID 34209967, 2021). "MDD and MRD determined by PCR for ALK-fusion transcripts are independent prognostic parameters for patients with ALK-positive anaplastic large cell lymphoma (ALCL)." (PMID 33921029, 2021). "Using SORE6, we identified and enriched CSL cells in ALK-positive anaplastic large cell lymphoma (ALK + ALCL)." (PMID 34287231, 2021). "For example, the prognosis of anaplastic lymphoma kinase (ALK)-positive anaplastic large cell lymphoma (ALCL) is significantly better than that of other subtypes of PTCL." (PMID 34264417, 2021). "ALK-positive anaplastic large cell lymphoma (ALK+ ALCL) is a rare subtype of peripheral T-cell Non-Hodgkin Lymphoma (NHL), and is more common in children and young adults." (PMID 33412518, 2021). "Anaplastic lymphoma kinase (ALK) + anaplastic large cell lymphoma (ALCL) is considered as a good prognosis lymphoma." (PMID 33847688, 2021). "Previously it was shown that autophagy contributes to crizotinib resistance in ALK-positive anaplastic large cell lymphoma (ALK + ALCL)." (PMID 33430343, 2021). "In Japan, alectinib is only available ALK-TKI for the treatment of anaplastic large cell lymphoma (ALCL)." (PMID 33627640, 2021). "Some tumors, such as ALK+ anaplastic large cell lymphoma (ALCL), lose the expression of SQLE, which mediates the generation of cholesterol from squalene, indicating that these tumors are dependent on exogenous cholesterols." (PMID 33801564, 2021). "We report a case of a 45‐year‐old female who developed an ALK‐positive anaplastic large cell lymphoma (ALCL) 9 years after renal transplant." (PMID 35847710, 2020). "Anaplastic lymphoma kinase positive anaplastic large cell lymphomas (ALK+ ALCL) are a distinct clinicopathologic non-Hodgkin’s lymphoma, primarily occurring in children and young adults." (PMID 33066037, 2020). "Anaplastic lymphoma kinase positive anaplastic large cell lymphomas (ALK+ ALCL) are an aggressive pediatric disease." (PMID 33066037, 2020). "During the time of classification, “9714/3” coded for anaplastic large cell lymphoma expressing the lymphoma kinase (ALK-positive) and thus describes a different entity than BI-ALCL." (PMID 32344893, 2020). "Anaplastic large cell lymphoma (ALCL) with ALK-translocation constitutes an aggressive lymphoma with high sensitivity to anthracycline-based chemotherapy." (PMID 33134180, 2020). "Anaplastic large cell lymphoma (ALCL) represents a heterogeneous group of T-cell lymphomas, which characteristically express CD30 and are associated with translocations involving the anaplastic lymphoma kinase (ALK) gene on chromosome 2p23." (PMID 32914146, 2020). "Anaplastic lymphoma kinase (ALK)–positive anaplastic large cell lymphoma (ALCL) exhibits a highly aggressive clinical course." (PMID 33088554, 2020). "However, except for ALK + anaplastic large-cell lymphoma (ALCL), most peripheral T-cell lymphomas (PTCLs) are highly malignant and have an aggressive disease course and poor clinical outcomes, with poor remission rates and frequent relapse after first-line treatment." (PMID 33160401, 2020). "We and others have described the effects of the NPM-ALK/STAT3 axis on miRNA expression in ALK-positive anaplastic large cell lymphoma (ALCL)." (PMID 31878193, 2019). "Conversely, the ALK+ anaplastic large cell lymphomas (ALK+ALCL) were the least sensitive (p = 0.0095)." (PMID 31167506, 2019). "Anaplastic lymphoma kinase (ALK) was first successfully cloned in 1994 when it was reported in the context of a fusion protein in cases of anaplastic large cell lymphoma (ALCL)." (PMID 31366041, 2019).
anaplastic large cell lymphoma (continued). "TYK2 is a member of the JAK family of tyrosine kinases that is involved in chromosomal translocation-induced fusion proteins found in anaplastic large cell lymphomas (ALCL) that lack rearrangements activating the anaplastic lymphoma kinase (ALK)." (PMID 30131584, 2019). "The association between activating ALK mutations and MYC or MYCN is observed in other malignancies including neuroblastoma and anaplastic large cell lymphoma (ALCL)." (PMID 29507657, 2018). "NPM (nucleophosmin)-ALK (anaplastic lymphoma kinase) is an oncogenic tyrosine kinase that is involved in the development of anaplastic large cell lymphoma (ALCL)." (PMID 29510549, 2018). "Moreover, it was reported that in the colorectal cancer cell lines HCT116 and DLD1 and in ALK-positive anaplastic large cell lymphoma (ALCL), an aggressive form of non-Hodgkin lymphoma, DDX11 protein expression level is reduced, leading to genomic instability and chromatid cohesion defects." (PMID 30469382, 2018). "ALK-negative anaplastic large cell lymphomas (ALCL, ALK-) are CD30+ T-cell neoplasms, which lack anaplastic large cell lymphoma kinase (ALK) rearrangement and corresponding protein." (PMID 29370815, 2018). "Like other receptor tyrosine kinases, wild-type ALK is activated by the binding of its ligand (such as augmentor α), whereas, mutant ALK is located in the cytosol and is constitutively activated in many cancer cells, such as anaplastic large cell lymphoma, in a ligand-independent manner." (PMID 30404198, 2018). "ALK gene alterations have been well reported to play a key role in the pathogenesis of several cancers (inflammatory myofibroblastic tumors and neuroblastomas) after it was first discovered in anaplastic large cell lymphoma and hence the name anaplastic lymphoma kinase." (PMID 30687633, 2018). "Furthermore, expression of granulysin was observed in rare cases of T cell lymphomas with a cytotoxic phenotype (i.e. ALK-negative anaplastic large cell lymphoma (26%), enteropathy-associated T cell lymphoma (12%) and peripheral T cell lymphoma, NOS (4%))." (PMID 30151671, 2018). "First discovered as a partner to Nucleophosmin 1 (NPM1) in the NPM-ALK fusion oncoprotein of Anaplastic Large Cell Lymphoma (ALCL), Anaplastic Lymphoma Kinase (ALK) is a receptor tyrosine kinase and a member of the insulin receptor superfamily." (PMID 29642598, 2018). "With the exception of ALK+ anaplastic large cell lymphoma (ALCL) they have a poor clinical outlook with a 25 to 30% 5-year overall survival." (PMID 30242208, 2018). "We further investigated the effect of c-Jun and JunB knock-down on proliferation in another CD30–positive lymphoma, anaplastic lymphoma kinase-positive, anaplastic large cell lymphoma (ALK+ ALCL)." (PMID 30375407, 2018). "Anaplastic lymphoma kinase (ALK)-positive anaplastic large cell lymphoma (ALCL) is a biologically defined disease of children and young adults." (PMID 29642597, 2018). "The first identification of ALK occurred in anaplastic large cell lymphoma (ALCL) as the product of a gene rearrangement." (PMID 29455642, 2018). "Together with the evidence of upregulation of HIF-1α mRNA in ALK-positive anaplastic large cell lymphoma under normoxic condition, we therefore hypothesized that ALK signaling may contribute to tumor growth through hypoxia-independent neovascularization in GBMs." (PMID 28837676, 2017). "A previous study demonstrated that the accumulation of NPM-ALK in the cytoplasm induced cell death by excessive ALK signaling in anaplastic large cell lymphoma (ALCL) cells." (PMID 28717217, 2017). "Immune system recognition of the ALK protein has been demonstrated in patients with ALK-positive anaplastic large cell lymphoma (ALCL)." (PMID 29190913, 2017). "Anaplastic large cell lymphoma (ALCL) is often driven by a constitutively active tyrosine kinase, the nucleophosmin-anaplastic lymphoma kinase (ALK)." (PMID 28848546, 2017).
anaplastic large cell lymphoma (continued). "A chromosomal translocation giving rise to an abnormal nucleophosmin (NPM)‐anaplastic lymphoma kinase (ALK) fusion protein is characteristic for pediatric anaplastic large cell lymphoma (ALCL)." (PMID 28556516, 2017). "The NOVA1 expression level varied according to the subtype; it was higher in angioimmunoblastic T cell lymphoma (AILT), anaplastic lymphoma kinase (ALK)-negative anaplastic large cell lymphoma (ALCL), and T-LBL, but it was lower in ALK-positive ALCL." (PMID 27398102, 2016). "ALK-positive Anaplastic Large Cell Lymphoma (ALCL) represents a subset of Non-Hodgkin Lymphoma whose treatment benefited from crizotinib development, a dual ALK/MET inhibitor." (PMID 27662658, 2016). "Chromosomal rearrangements involving the ALK gene occur in different malignant conditions, including anaplastic large cell lymphoma (ALCL) and inflammatory myofibroblastic tumor (IMT)." (PMID 28330089, 2016). "In the nodal T cell lymphomas, the major subtypes are PTCL, not otherwise specified (PTCL-NOS), angioimmunoblastic T cell lymphoma (AITL), anaplastic lymphoma kinase (ALK)-positive anaplastic large cell lymphoma (ALCL) and ALK-negative ALCL." (PMID 27071634, 2016). "A large subset of anaplastic large cell lymphoma (ALCL) patients harbour a somatic aberration in which anaplastic lymphoma kinase (ALK) is fused to nucleophosmin (NPM) resulting in a constitutively active signalling fusion protein, NPM-ALK." (PMID 27669408, 2016). "ALK-positive anaplastic large cell lymphoma (ALK + ALCL) is a specific type of non-Hodgkin lymphoma of null/T cell lineage occurring most frequently in young adults and children." (PMID 27821172, 2016). "Anaplastic lymphoma kinase (ALK), a tyrosine kinase receptor residing on chromosome 2p23 was first described in a subset of anaplastic large cell lymphoma (ALCL) patients as part of a chromosomal rearrangement with nucleophosmin as a fusion partner." (PMID 26384210, 2015). "ALK inhibitor crizotinib has shown potent antitumor activity in children with refractory Anaplastic Large Cell Lymphoma (ALCL) and the opportunity to include ALK inhibitors in first-line therapies is oncoming." (PMID 25874976, 2015). "Since anaplastic large cell lymphoma (ALK+ ALCL) cell lines were the most sensitive to the pan-PIMi, we tested the simultaneous inhibition of ALK and PIM kinases and found a strong synergistic effect in ALK+ ALCL cell lines." (PMID 25386922, 2014). "Translocations involving ALK have previously been identified in anaplastic large cell lymphomas (ALCL), and in a rare mesenchymal neoplasm known as inflammatory myofibroblastic tumor or inflammatory pseudotumor." (PMID 25077070, 2014). "ALK, a receptor tyrosine kinase in the insulin receptor superfamily, was initially identified in activated oncogenic fusion forms, most common being the nucleophosmin ALK in anaplastic large-cell lymphomas and paediatric cancer as well as neuroendocrine tumors." (PMID 25054154, 2014). "Persistent expression of SOCS1 and/or SOCS3 is observed in several haematological malignancies such as cutaneous T cell lymphoma (CTCL), chronic myeloid leukemia (CML), ALK+ anaplastic large cell lymphoma (ALCL), and some acute leukemia." (PMID 24757565, 2014). "Many of these breakpoints corresponded to known gene fusions, including BCR/ABL1 in CML, FIP1L1/PDGFRA in eosinophilic leukemia, and NPM1/ALK in anaplastic large cell lymphoma (ALCL)." (PMID 23637631, 2013). "Activation of mTOR contributes to tumor cell survival in ALK (anaplastic lymphoma kinase)-positive ALCL (anaplastic large cell lymphoma), mantle cell lymphoma, childhood B-precursor ALL, T-ALL, and AML." (PMID 23431463, 2013). "Excluding ALK+ anaplastic large cell lymphoma, which is associated with a good prognosis (5-year OS 70%), and ALK-negative anaplastic large cell lymphoma (5-year OS 49%), the overall 5-year survival for other common subtypes of peripheral T-cell lymphomas is about 30–35%." (PMID 23755375, 2013).
anaplastic large cell lymphoma (continued). "Anaplastic large cell lymphoma (ALCL) anaplastic lymphoma kinase positive (ALK+) is one of the subcategories of the mature T-cell neoplasms." (PMID 24224107, 2013). "In order to understand whether the effects mediated by IL-10 neutralization were melanoma-specific or could be replicated in a different unrelated type of tumor, the same experiment was performed using mouse anaplastic large cell lymphoma (ALCL) cells (ALK+ VAC cells,) as challenging tumor." (PMID 23663506, 2013). "Notwithstanding, recent study found aberrant expression of IL-22R1 on anaplastic lymphoma kinase positive anaplastic large cell lymphoma (ALK+ ALCL) cell lines." (PMID 23236476, 2012). "Other studies, however, suggest that it might be a true neoplasm due to the presence, at the myofibroblastic component, of a fusion gene involving the ALK gene, a tyrosine kinase oncogen located on chromosome 2p23, initially found to be arranged in anaplasic large cell lymphomas." (PMID 22805416, 2012). "ALK-positive anaplastic large cell lymphomas (ALK+ ALCL) are a distinct subset of non-Hodgkin lymphomas with a T or null cell immunophenotype recognized by the World Health Organization Classification Scheme for hematological neoplasms." (PMID 22852078, 2012). "With notable exceptions such as ALK+ anaplastic large cell lymphoma (ALCL, ALK+), the molecular abnormalities in PTCL remain poorly characterised." (PMID 21887344, 2011). "Anaplastic lymphoma kinase (ALK)-positive anaplastic large cell lymphoma (ALCL) is an aggressive T-cell lymphoma." (PMID 21281497, 2011). "Histopathological evaluation demonstrated large ALK-positive lymphoma cells suggestive of anaplastic large cell lymphoma of T- or 0-lineage (ALCL) and treatment was initiated accordingly." (PMID 21494621, 2011). "Interestingly, fusions of CLTC with the anaplastic lymphoma kinase (ALK) have been encountered in inflammatory myofibroblastic tumors and anaplastic large-cell lymphomas, whereas fusions with the transcription factor TFE3 have been encountered in renal cell carcinomas (RCC)." (PMID 21152103, 2010). "The recent development of antibodies against the anaplastic large cell lymphoma kinase (ALK) has further refined the immunohistochemical analysis of ALCL." (PMID 21331150, 2010). "In ALK+ anaplastic large-cell lymphoma other factors such as CD56 may indicate a poor prognosis." (PMID 16623775, 2006). "A 26-year-old patient was diagnosed with anaplastic lymphoma kinase negative anaplastic large cell lymphoma [ALK-ALCL] associated with synchronous malignant histiocytosis." (PMID 39810204, 2025). "ALK-positive anaplastic large cell lymphoma (ALCL) needs to be considered in the differential diagnosis with ALK-positive LBCL due to morphology, CD20 negativity and ALK expression." (PMID 40869163, 2025). "Findings were consistent with anaplastic lymphoma kinase negative anaplastic large cell lymphoma [ALK-ALCL] associated with synchronous malignant histiocytosis according to the 2016 revised classification criteria of the Histiocyte Society." (PMID 39810204, 2025). "ALCL is categorized into three subtypes: ALK-positive anaplastic large cell lymphoma (ALK+ALCL), ALK-negative anaplastic large cell lymphoma (ALK-ALCL), and breast implant-associated anaplastic large cell lymphoma (BIA-ALCL)." (PMID 41584605, 2025). "ALK rearrangements were initially identified in large-cell lymphomas, but the discovery of the EML4-ALK fusion in NSCLC in 2007 established ALK as a key oncogenic driver in this disease." (PMID 41373672, 2025). "Our case report describes another instance of CD8+ to CD4+ phenotypic shift of MF, but with associated transformation to anaplastic lymphoma kinase (ALK)-negative anaplastic large cell lymphoma (ALCL) - the first documented case of its kind." (PMID 40166794, 2025).
anaplastic large cell lymphoma (continued). "In Mexico, ALCL was identified in over 50% of pediatric cases diagnosed with large cell lymphomas exhibiting anaplastic morphology, all of which tested positive for CD30 and ALK markers." (PMID 41255846, 2025). "The Immuno ALCL trial was designed to investigate whether genetic variability in 13 cancer-immunity relevant genes correlated with clinical features and outcome of anaplastic lymphoma kinase (ALK)-positive anaplastic large cell lymphoma (ALCL) patients." (PMID 41469691, 2025). "ALK+ anaplastic large cell lymphoma (ALCL) is an aggressive lymphoma characterized by the presence of the nucleophosmin-anaplastic lymphoma kinase (NPM-ALK) oncogene resulting from a chromosomal rearrangement between chromosome 2 and chromosome 5 which drives lymphomagenesis." (PMID 40647524, 2025). "In anaplastic large cell lymphoma (ALCL), ALK gene rearrangements frequently lead to fusion protein expression, driving malignant transformation and expansion of lymphoid cells." (PMID 41614760, 2025). "Dysregulated ALK signaling has been extensively implicated in a range of solid tumors, particularly non-small cell lung cancer (NSCLC), anaplastic large cell lymphoma (ALCL), and neuroblastoma (NB)." (PMID 40872599, 2025). "We report here the first case of anaplastic lymphoma kinase negative anaplastic large cell lymphoma [ALK-ALCL] associated with synchronous malignant histiocytosis where the histiocytic component lacked the TCR gene rearrangement found in the lymphoma cells." (PMID 39810204, 2025). "ALK-positive anaplastic large cell lymphoma (ALCL) may show sinusoidal involvement, but exclusive intrasinusoidal infiltration of lymph nodes is exceptionally rare." (PMID 41366174, 2025). "ALK, first identified in 1994 in the AMS3 cell line derived from anaplastic large cell lymphoma, is a transmembrane protein composed of 1,620 amino acids and is a member of the insulin receptor family." (PMID 39703852, 2024). "Furthermore, loss of PTPN1 and PTPN2 expression was recently identified as an important driver of anaplastic large cell lymphoma (ALCL) resistance to anaplastic lymphoma kinase (ALK) inhibitors." (PMID 38334623, 2024). "Notably, subgroup analyses within the study included patients with AITL and ALK+ anaplastic large cell lymphoma (ALK+ ALCL)." (PMID 39409979, 2024). "Historically, anaplastic lymphoma kinase (ALK) has been studied in several cancer types, including anaplastic large-cell lymphoma, adenocarcinoma of the lung, epithelioid fibrous histiocytoma, and inflammatory myofibroblastic tumor (IMT)." (PMID 38390852, 2024). "Anaplastic lymphoma kinase (ALK) was first identified as a potential cancer drug target 15 years prior, when it was found as a fusion kinase with nucleophosmin in anaplastic large cell lymphoma." (PMID 39335535, 2024). "In 1994, a t translocation was first described in anaplastic large cell lymphoma, resulting in an NPM (nucleophosmin)-ALK fusion gene, an event that is detected in 60%–80% of ALCL." (PMID 38953007, 2024). "Our study also found that most T/Natural Killer cells NHL expressed STAT-3, apart from Anaplastic Large cell lymphoma (ALCL) and Anaplastic Lymphoma Kinase-positive (ALK-positive)." (PMID 37175040, 2023). "The four entities of anaplastic large cell lymphomas (ALCLs) are identical in both proposals: ALK-positive (ALK+) and ALK-negative (ALK−) ALCL, primary cutaneous ALCL (within the spectrum of CD30-positive cutaneous T cell lymphoproliferative disorders), and breast implant-associated (BIA-)ALCL." (PMID 38047948, 2023). "For anaplastic large cell lymphoma, the use of CD3 and other T-cell markers, as well as CD4, CD8, CD20, PAX5, ALK, and CD30, are helpful for diagnosis." (PMID 37958219, 2023). "A study conducted an evaluation of IRF8 expression in CHL (74 cases), NLPHL (seven cases), ALK-negative anaplastic large cell lymphoma (ALCL) (15 cases), and ALK-positive ALCL (four cases)." (PMID 38179383, 2023).